PCDH9 (protocadherin 9)
Description:
Potential calcium-dependent cell-adhesion protein.
Tractability: Antibody: UniProt places it where antibodies can reach, with medium confidence; UniProt predicts a signal peptide or a membrane-spanning region; its Gene Ontology location is reachable by antibodies, with medium confidence. PROTAC: its protein half-life has been measured.
Gene: Protein-coding gene on chromosome 13 (66,302,834 to 67,230,445, reverse strand). Ensembl gene ENSG00000184226.
Subcellular location: Cell membrane
Subcellular location (Human Protein Atlas): Centrosome; Nucleoplasm
Gene Ontology:
Molecular function: cell adhesion molecule binding; calcium ion binding
Biological process: cell adhesion; forebrain development; homophilic cell-cell adhesion
Cellular component: glutamatergic synapse; plasma membrane; membrane; synaptic membrane
Genetic constraint (gnomAD): Loss-of-function variants: 17 observed, 62.37 expected, observed/expected ratio (o/e) 0.27, 90% interval 0.19 to 0.41. The upper end of that interval is the gene's LOEUF score, 0.41, which puts it in group 1 of 6, group 1 being the genes least tolerant of losing a copy. Missense variants: 1,152 observed, 1,448.8 expected, observed/expected ratio (o/e) 0.8, 90% interval 0.76 to 0.83. Synonymous variants: 517 observed, 544 expected, observed/expected ratio (o/e) 0.95, 90% interval 0.88 to 1.02.
Homologues: Orthologues: chimpanzee PCDH9 (99% identical), macaque PCDH9 (99% identical), dog PCDH9 (99% identical), pig PCDH9 (99% identical), rabbit PCDH9 (99% identical), rat Pcdh9 (99% identical), guinea pig PCDH9 (98% identical), mouse Pcdh9 (96% identical), tropical clawed frog pcdh9 (92% identical), zebrafish pcdh9 (72% identical), zebrafish pcdh11 (6% identical). Paralogues in human: PCDH11X (54% identical), PCDH11Y (51% identical), PCDH7 (39% identical), PCDH1 (37% identical), PCDH20 (26% identical), CDH23 (20% identical), DCHS2 (19% identical), DCHS1 (19% identical), CDHR2 (18% identical), CDH4 (16% identical), CDH2 (16% identical), CDH1 (15% identical), and 21 more.
Diseases named in the same sentence as PCDH9 in open-access papers:
PCDH9 is named in the same sentence as 52 diseases in open-access papers, as found by Europe PMC text mining. Sharing a sentence is not in itself a finding about the gene and the disease. The quoted sentences say what the papers report.
glioma (16 papers, 2015 to 2023). A benign or malignant brain and spinal cord tumor that arises from glial cells (astrocytes, oligodendrocytes, ependymal cells). "Some authors have indicated that the downregulation, loss of expression, and deletion of PCDH9 were associated with the progression of prostate cancer, epithelial ovarian cancer, glioma, and gastric cancer." (PMID 37629695, 2023). "PCDH9 gene encodes the protein named protocadherin-9 (PCDH9), which is known as a tumor suppressor in glioma, hepatocellular carcinoma, and ovarian cancer." (PMID 35903688, 2022). "Expression of PCDH9 was downregulated in glioma in comparison to normal brain tissue, and loss of PCDH9 expression was associated with a higher histological grade and shorter survival time of patients." (PMID 29649113, 2018). "We further analyzed the potential association between miR-215-5p and PCDH9 mRNA levels in glioma tissues and normal brain tissues." (PMID 28055966, 2017). "We found a strong association between miR-215-5p up-regulation and PCDH9 down-regulation in gliomas." (PMID 28055966, 2017). "Then, we confirmed the association between miR-215-5p up-regulation and PCDH9 down-regulation in glioma samples and cell lines." (PMID 28055966, 2017). "PCDH9 is frequently lost in hepatocellular carcinomas, its down-regulation is associated with tumor cell migration, and PCDH9-negative tumors correlate with significantly shorter survival times for glioma patients." (PMID 26039411, 2015). "Protocadherin-7 (PCDH7) and protocadherin-9 (PCDH9) were identified and experimentally validated as targets of miR-155-3p and miR-155-5p, respectively, within primary glioma cells." (PMID 35611569, 2022). "Extensive studies have reported that PCDH9 gene expression was silenced by microRNAs, such as miR-215-5p and miR-589-3p in glioma cells and miR-200a-3p in ovarian cancer cells." (PMID 35903688, 2022). "With regard to glioma, a recent study reported that miR-155-5p enhances the migration and invasion capability of glioma by directly targeting PCDH9 and activating the Wnt/β-catenin signaling pathway." (PMID 35986010, 2022). "MiR-215-5p binds to both promoter and 3’ UTR of PCDH9 and inhibits the expression of PCDH9 in glioma." (PMID 29471827, 2018). "Decreased expression of PCDH9 has been reported in glioma, gastric cancer, hepatocellular carcinoma, prostate cancer and ovarian cancer, among other neoplasms." (PMID 29649113, 2018). "In this study, to search the dual inhibitory miRNAs which suppress PCDH9 expression in gliomas, we performed an integrative analysis of databases including miRDB, TargetScan, microPIR and miRCancer." (PMID 28055966, 2017). "In summary, we find that synergetic suppression of miR-215-5p on PCDH9 expression is more efficient than targeting the promoter or 3′UTR alone in gliomas, and miR-215-5p promotes aggressive glioma phenotypes via inhibiting PCDH9 expression." (PMID 28055966, 2017). "Consistently, PCDH9 mRNA levels in gliomas were down-regulated compared to those in normal brain tissues." (PMID 28055966, 2017). "We identified three candidate miRNAs which were predicted to bind both the promoter and 3′UTR of PCDH9 and up-regulated in gliomas." (PMID 28055966, 2017). "An un-biased integrative study combining chromosomal alterations and gene expression data identifies PCDH9 as a potential tumor suppressor in gliomas." (PMID 28055966, 2017). "Moreover, the expression of PCDH9 was significantly lower in high-grade and worse histological type of tumors of glioma, gastric, and prostatic cancers." (PMID 36452505, 2022). "Therefore, PCDH9 expression will be down-regulated at the transcriptional and post-transcriptional levels in glioma." (PMID 33330058, 2020). "Downregulation of PCDH9 expression in glioma has been reported by Wang." (PMID 29649113, 2018).
glioma (continued). "Then, we validated miR-215-5p up-regulation and PCDH9 down-regulation in glioma samples and demonstrated that miR-215-5p could inhibit the mRNA and protein levels of PCDH9 in glioma cell lines by targeting its promoter and 3′ UTR at the same time." (PMID 28055966, 2017). "Our study provides evidence for a novel dual inhibition of PCDH9 by miR-215-5p in gliomas and suggests that miR-215-5p might be a therapeutic target for the treatment of gliomas." (PMID 28055966, 2017). "Given the important roles of PCDH9 in gliomas, the regulatory mechanism of PCDH9 expression is critical but almost unknown." (PMID 28055966, 2017). "PCDH9 knock-down exacerbates the tumor phenotypes in glioma cell lines." (PMID 28055966, 2017). "To further confirm if miR-215-5p could inhibit PCDH9 expression, we over-expressed miR-215-5p at the concentration of 5-100 nM in glioma cell line U251." (PMID 28055966, 2017). "As previous study shows that PCDH9 plays important roles in proliferation, tumor formation and apoptosis, we sought to determine if miR-215-5p also promotes these tumor phenotypes via inhibiting PCDH9 expression in two glioma cell lines U251 and U87." (PMID 28055966, 2017). "Our previous studies showed down-regulation of PCDH9 protein levels in gliomas." (PMID 28055966, 2017). "Moreover, we demonstrate that miR-215-5p promotes cell proliferation, clone formation, migration and suppresses apoptosis of gliomas by down-regulating PCDH9 expression." (PMID 28055966, 2017). "Our study provides a novel mechanism for the PCDH9 dwon-regulation and suggests that miR-215-5p might be a therapeutic target in gliomas." (PMID 28055966, 2017). "In this study, we first predicted the miRNAs which might bind to both the promoter and 3′UTR of PCDH9 by integrative analysis and then measured the expression levels of candidate miRNAs and PCDH9 in glioma samples." (PMID 28055966, 2017). "PCDH9 has been reported to be a tumour-suppressor gene in human gliomas." (PMID 28611294, 2017). "Moreover, miR-215-5p promotes aggressive phenotypes of glioma cell lines through inhibiting PCDH9 expression." (PMID 28055966, 2017). "Interestingly, several of these L2b-targets, which are not bound by AGO2 in glioblastoma, are implicated in glioma, such as PCDH9 and AQP4 and show similar non-canonical target sites as we found in other L2-miRNA targets." (PMID 30865625, 2019). "Moreover, PCDH9 mRNA levels in high-grade gliomas were lower than those in low-grade gliomas." (PMID 28055966, 2017). "Moreover, miR-215-5p could increase glioma cell proliferation, clone formation, in-vitro migration and reduce apoptosis via inhibiting PCDH9 expression." (PMID 28055966, 2017). "Protocadherin 9 (PCDH9), a member of cadherin superfamily, facilitates cell-cell adhesion and is downregulated in glioma." (PMID 29471827, 2018). "Thus, abnormal microRNAs might induce PCDH9 down-regulation in gliomas." (PMID 28055966, 2017). "Thus, insights from PCDH9 regulation might bring new opportunity for glioma treatment." (PMID 28055966, 2017). "We further validated that miR-215-5p could inhibit PCDH9 expression by binding its promoter and 3′UTR in glioma cell lines." (PMID 28055966, 2017). "There was a significant negative correlation between miR-215 and PCDH9 mRNA level in gliomas (R=-0.43, P=0.0166)." (PMID 28055966, 2017). "Similarly, low editing of miR-589 in glioma was reported to change its specificity from disintegrin and metalloproteinase domain-containing protein 12 (ADAM12), a primary target of miR-589, towards protocadherin 9 (PCDH9), thereby promoting cell migration and invasion." (PMID 31835747, 2019). "The expression of PCDH9 in various tumor tissues was significantly lower than that in healthy tissues, such as prostate, gastric, HCC, non-nodal mantle cell lymphoma, glioma, and nodal/hepatic metastatic tissues." (PMID 36387162, 2022).
hepatocellular carcinoma (13 papers, 2015 to 2026). A malignant tumor that arises from hepatocytes. "Another investigation found that salivary lnc-PCDH9–13:1 was a specific and sensitive diagnostic marker for hepatocellular carcinoma which may enforce that salivary lncRNAs could be a valuable non-invasive approach for cancer diagnosis." (PMID 38087258, 2023). "PCDH9, a tumor suppressor in human hepatocellular carcinoma, was upregulated at 15 days after reovirus treatment administration, after being less expressed at 8 days after the treatment." (PMID 37873786, 2023). "The previous investigations of hepatocellular carcinoma (HCC) found that PCDH9 suppresses HCC cells by inducing cell cycle arrest at G0/G1 phase." (PMID 36452505, 2022). "An investigation reported hypermethylation of Pcdh9 (TSG) can induce cell cycle arrest at G0/G1 phase in hepatocellular carcinoma." (PMID 35263365, 2022). "In hepatocellular carcinoma, downregulation of PCDH9 expression is correlated with portal vein invasion, increased tumour cell migration and increased EMT." (PMID 29649113, 2018). "PCDH9 plays important roles in many types of cancer and its down-regulation is also found in gastric cancer and hepatocellular carcinoma." (PMID 28055966, 2017). "In hepatocellular carcinoma (HCC) cells, the loss of PCDH9 expression facilitated tumour-cell migration and epithelial-mesenchymal transition (EMT)." (PMID 28611294, 2017). "PCDH9 has been shown to act as a tumor suppressor in human hepatocellular carcinoma." (PMID 37873786, 2023). "Previous investigations of hepatocellular carcinoma (HCC) found that PCDH9 suppresses HCC cells by inducing cell cycle arrest at G0/G1 phase." (PMID 36387162, 2022). "LINC00355, also named as lnc-PCDH9-13:1, has been found to abnormally expressed in multiple malignancies such as esophageal squamous cell carcinoma, papillary renal cell carcinoma, and hepatocellular carcinoma (HCC)." (PMID 33381451, 2020).
major depressive disorder (7 papers, 2021 to 2026). An episode of depression lasting two or more weeks without an intervening episode of mania. "Here, we uncover a novel activity-dependent signaling pathway for Pcdh9, a protocadherin linked to Autism Spectrum Disorder and Major Depressive Disorder." (PMID 41685090, 2026). "Low levels of PCDH9 in brain and peripheral blood have been associated with major depressive disorder." (PMID 40697488, 2025). "Moreover, a meta-analysis of genome-wide association studies highlighted the significant association of the single-nucleotide polymorphism (SNP) rs9540720 in the PCDH9 gene with major depression disorder and cognitive function impairment." (PMID 40170191, 2025). "For example, microglia showed a reduced expression of Csmd1, a complement regulatory gene linked to familial epilepsy and schizophrenia (Schizophrenia Psychiatric Genome‐Wide Association Study & C, 2011), and of the protocadherin Pcdh9, which is a risk factor for major depressive disorder." (PMID 33644903, 2021). "In addition to CACNA1C, we found several DMRs in Pcdh9, another susceptibility gene for depression, further highlighting that the shared pathways between prenatal stressors may reprogram key biological systems involved in mental health." (PMID 34828381, 2021). "It has been demonstrated that PSEN2 knock-in mice exhibit severe depressive behavior, and PCDH9 and ANKK1 have also been reported as risk genes for depression." (PMID 40075226, 2025). "The seven positively selected depression-associated genes we identified in the human lineage are involved in brain development (PSEN2, ANKK1, PCDH9) and immunity (STAU1 and LYRM4), as highlighted in our results." (PMID 40075226, 2025).
prostate carcinoma (7 papers, 2018 to 2025). A carcinoma that arises from epithelial cells of the prostate gland. "The piR-001773 and piR-017184 regulate PCDH9 post-transcriptionally which promotes proliferation, invasion, and metastasis of prostate cancer cells and effectively promotes the growth of tumors in vivo and in vitro." (PMID 36733811, 2022). "The PCDH9 down-regulation in prostate cancer cells leads to an enhanced AKT phosphorylation and activity thereof." (PMID 36733811, 2022). "In prostate cancer, piR-001773 and piR-017184 synergistically regulate the transcription of protocadherin 9 (PCDH9) under homeostasis and thereby promote tumor invasion and metastasis." (PMID 34118972, 2021). "Scientific inquiries have identified piR‐001773 and piR‐017184 as being elevated in prostate cancer specimens, and these molecules are believed to regulate the expression levels of protocadherin 9 (PCDH9) in a posttranscriptional manner, thereby influencing disease pathology." (PMID 40737301, 2025). "Protocadherin 9 (PCDH9) is down-regulated in prostate cancer cells and acts as a tumor suppressor." (PMID 36733811, 2022).
gastric cancer (6 papers, 2017 to 2023). A primary or metastatic malignant neoplasm involving the stomach. "Loss of PCDH9 expression is associated with epithelial dif-ferentiation and cell metastasis in gastric cancer." (PMID 33369468, 2020). "Decreased PCDH9 expression is associated with the metastasis of gastric cancer cells." (PMID 36339718, 2022). "PCDH9 is a metastasis regulator, which is well-described in gastric cancer metastases in our previous study." (PMID 35903688, 2022). "Decreased expression of PCDH9 is frequent in metastases of human gastric cancer and its expression is an independent prognostic factor." (PMID 33369468, 2020). "Reduced expression of PCDH9 was also observed during the progression of gastric cancer." (PMID 29649113, 2018).
glioblastoma (6 papers, 2018 to 2024). The most malignant astrocytic tumor (WHO grade IV). "For example, miR-589–3p is edited by ADAR2 in normal brain cortices compared to de novo glioblastoma, which changes the target gene of miR-34a from the protocadherin 9 (PCDH9) to the metalloprotease Metalloproteinase 12 (ADAM12)." (PMID 36615779, 2022). "PCDH9 is downregulated in glioblastoma and overexpression of PCDH9 inhibits cellular invasion of glioma." (PMID 32523124, 2020). "Genetic abnormalities in SLC16A1 have been identified to cause congenital hyperinsulinism; PCDH9 is a non-clustered protocadherin, mutations in humans are associated with autism spectrum disorders and its expression in glioblastoma suggest a role as tumor suppressor." (PMID 30166318, 2018). "In the context of de novo glioblastoma, a highly aggressive brain cancer, ADAR2-mediated editing of miR-589-3p results in a shift from its regulation of the tumor suppressor PCDH9 to the modulation of ADAM12, effectively impeding glioblastoma invasion." (PMID 38911375, 2024). "Editing within miR-589–3p retargets the miRNA from the protocadherin PCDH9 to the metalloprotease ADAM12, which is involved in glioblastoma cell invasion." (PMID 34282776, 2021).
ovarian carcinoma (5 papers, 2018 to 2023). A malignant neoplasm originating from the surface ovarian epithelium. "In ovarian cancers, miR-200a-3p is shown to possess oncogenic potential, possibly by modulating Protocadherin 9, and increased expressions were associated with increased tumor size and metastasis." (PMID 37958433, 2023). "Decreased level of PCDH9 transcript was also observed in ovarian cancer tumours in comparison to normal ovarian epithelium." (PMID 29649113, 2018). "High levels of miR-200a-3p promote the proliferation of ovarian cancer cells by targeting PCDH9." (PMID 36339718, 2022). "FAM198B may act to favor tumor progression by interacting with numerous genes, such as the p-ERK/MMP-1 signaling pathway in lung adenocarcinoma, and S100A3, PCDH9, and SEMA3A genes in ovarian cancer." (PMID 35587159, 2022).
autism (4 papers, 2011 to 2024). Persistent deficits in social interaction and communication and interaction as well as a markedly restricted repertoire of activity and interest as well as repetitive patterns of behavior. "Variations in the genes TMPRSS4, TRPC4, and PCDH9 were consistently linked to autism across the two independent samples, highlighting the role of calcium signaling and cell adhesion molecules in the risk of autism-related disorders." (PMID 39766876, 2024). "Other previously reported autism candidate genes with suggestive roles in neurite regulation include PCDH9 (1.76E-03), CDH9 (6.00E-03) and CSMD3 (2.10E-02)." (PMID 21247446, 2011). "Surprisingly, we also identified associations with SNPs at the P<10−4 level near several genes previously implicated in autism, although not in our analysis of proband effects: PCDH9 and FOXP1." (PMID 24204716, 2013).
autism spectrum disorder (3 papers, 2017 to 2026). A spectrum of developmental disorders that includes autism, and Asperger syndrome. "The PCDH9 is also related with a neurological disease and autism spectrum disorder." (PMID 28993767, 2017).
breast cancer (3 papers, 2017 to 2023). A primary or metastatic malignant neoplasm involving the breast. "Regarding the list for down regulated genes associated with breast cancer, 3 genes were also present in our list (HLA-DPA1, PCDH9 and NCALD)." (PMID 29108258, 2017). "To further validate the identified target genes that showed significant changes in DE and DM patterns in response to maternal BSp treatment, we evaluated gene expression of Avpr2, Cyp4a12b, Dpp6, Gria2, Pcdh9 and Tspan11 genes in the offspring mammary tumors using qRT-PCR." (PMID 35263365, 2022). "As expected, seven of the TME prognostic genes (NOS2, SCG2, RGS3, EMP1, PDLIM4, PCDH9, and GFI1) showed dual functions in breast cancer progression." (PMID 36936167, 2023). "Seven of the 15 TME prognostic genes (NOS2, SCG2, RGS3, EMP1, PDLIM4, PCDH9, and GFI1) were involved in enhancing cell proliferation, destroying cell apoptosis, promoting cell invasion, or migration in breast cancer." (PMID 36936167, 2023).